IL1B (interleukin 1 beta)
Diseases named in the same sentence as IL1B in open-access papers (continued):
Sharing a sentence is not in itself a finding about the gene and the disease.
gout (continued). "Urate may give rise to inflammation through activation of the NLRP3 inflammasome, as in gout, followed by production of the pro-inflammatory cytokine IL-1β, whereas psoriasis is characterized by other inflammatory cytokines, such as TNF-α, IL-23 and IL-17." (PMID 33748660, 2021). "Butyrate, one of the main short-chain fatty acids (SCFAs) produced by the gut microbiota from dietary fiber that acts as a potent HDAC inhibitor, downregulates the transcription and release of IL-1β in PBMCs from patients with gout and healthy donors by blockading class I HDACs." (PMID 34829842, 2021). "Furthermore, the TNF-α is involved in the expression of pro-IL-1β mRNA and IL-1β protein in gout, triggering the MSU-induced inflammation in mice." (PMID 34359507, 2021). "Following tissue necrosis caused by MSU deposition, local ATP arising from the cellular release is increased, which can activate the P2X7 receptor leading to intra-and extracellular ion flow, activation of the NLRP3 inflammasome, and secretion of IL-1β, ultimately triggering a gout flare." (PMID 34925366, 2021). "Indeed, TNF-α directly promotes the expression of IL-1β protein and pro-IL-1β mRNA transcription in a mouse model of gout, and blocks TNF-α resulting in a dramatic amelioration of inflammation." (PMID 33959014, 2021). "Interestingly, promoting type I IFNs expression recently appeared as an attractive way to dampen IL-1β production in animal models for gout and RA." (PMID 34066649, 2021). "Also, prostaglandin E2 (PGE2), converted from arachidonic acid (AA) by cyclooxygenase (COX), contributes to the production of IL-1β, an important mediator in gout." (PMID 33505510, 2021). "The use of oral colchicine probably reduced the amounts of IL-1β secreted from gout PBMCs." (PMID 34992596, 2021). "Considering that in the gout model the NLRP3 inflammasome leads to the production of IL-1β and that neutrophils represent the main source of this cytokine, our findings indicate that the regulatory effect of Ac2-26 on NLRP3 activation could be via Fpr." (PMID 33440601, 2021). "Our data are in line with findings implicating NET protease–processed IL-1β in gout attacks and of neutrophil protease-generated IL-33 in acute lung injury, pointing to neutrophil proteases generating NET-associated IL-33 with high interferogenic activity in the context of lupus." (PMID 34554930, 2021). "Various genetic variations in the P2RX7 gene, coding for the P2X7 receptor implicated in inflammasome activation and probably a key regulator of IL-1β production by MSU crystals during acute gout flares, have been reported to be associated with gout: rs1653624, rs7958316, rs17525809, and rs3751142." (PMID 33926105, 2021). "As a result, various cytokines and chemokines are released, and in particular, IL-1β and TNF-α promote the recruitment of neutrophils, resulting in the inflammation of gouty arthritis through the release of a large amount of proinflammatory substances such as IL-1β, TNF-α, and IL-6." (PMID 34564665, 2021). "We hypothesized that gout PBMCs display enhanced IL-1β secretion due to increased phagocytosis of urate crystals by monocytes which can be suppressed by rhPRG4, and rhPRG4’s anti-inflammatory effect is PP2A-dependent." (PMID 34992596, 2021). "While gout PBMCs had variable responses to IL-1RA and rhPRG4, both treatments showed biologically meaningful anti-inflammatory effects against gout PBMCs with substantial IL-1β release." (PMID 34992596, 2021). "Given the anti‐inflammatory properties of IL‐38,28 such as its ability to block IL‐1β upregulation in mouse models of gouty arthritis, we investigated whether IL‐38 can block the induction of trained immunity." (PMID 33620105, 2021). "MSU phagocytosis was higher in gout monocytes resulting in higher ROS and IL-1β secretion." (PMID 34992596, 2021).
gout (continued). "Besides ATP, other purinergic metabolites, such as adenosine diphosphate (ADP) and adenosine, can bind to the corresponding purinergic receptors affecting IL-1β secretion in gout." (PMID 34925366, 2021). "The synergy between long-chain free fatty acids, released after food intake, and MSU crystals for the release of IL-1β and induction of inflammation might represent the missing link between metabolic changes, inflammasome activation, and gout attacks." (PMID 33926105, 2021). "5'UTR hypomethylation is associated with gene upregulation, and hypomethylated PRKCZ might therefore increase PRKCZ expression, subsequently increasing IL-1β production in macrophages and facilitating gout." (PMID 33493135, 2021). "An inflammasome-independent mechanism can also activate IL-1β in gout." (PMID 33926105, 2021). "IL-1β is a key inflammatory factor that mediates gouty arthritis." (PMID 34721647, 2021). "In addition, β-carotene reduced IL-1β secretion by human synovial cells isolated from patients with gout showing a potential inhibitory effect of β‐carotene on human gout." (PMID 33534121, 2021). "This inhibition might reduce the levels of proinflammatory factors (TNF-α and IL-1β) and alleviates the inflammatory response in gouty arthritis." (PMID 34803702, 2021). "Inflammatory cytokines, especially IL-1β, are key mediators of gout inflammation." (PMID 35116032, 2021). "Finally, MSU-induced PMN-MDSCs produced higher levels of IL-1β, which mediated gout inflammatory progression." (PMID 33154749, 2020). "We reason here that IL-33, after being released from macrophages, may act in an autocrine manner to induce CXCL1, CCL3 and IL-1β production via ST2 in macrophages during gout." (PMID 33204337, 2020). "Thus, the release of IL-1β mediated by inflammasome and the rapid recruitment of neutrophils lead to acute inflammatory episodes in gout patients." (PMID 33568990, 2020). "As MSU crystal can activate the NLRP3 inflammasome and IL‐1β secretion to trigger the gout flare." (PMID 32656909, 2020). "Given the roles of PGGT1B, INSIG1, ANGPTL2, JNK1, UBAP1, RAPTOR, and CNTN5 in regulating IL-1β or gouty inflammation and differential methylation of these genes in gout, the next important topic is the consequence of manipulating the respective signaling pathways." (PMID 32630231, 2020). "Additionally, an improvement of MSU-induced elevation of IL-1β concentration was found in JQ-1 rats, affirming the protection of JQ-1 from gouty arthritis." (PMID 33162822, 2020). "However, this dogma regarding the central role of NLRP3 in gout has been challenged 23, 24, although IL-1β remains a crucial cytokine in the development of the disease." (PMID 32104502, 2020). "In the context of hypermethylation-decreased transcription, hypermethylated PGGT1B might result in reduced PGGT1B transcription, subsequently augmenting IL-1β production in macrophages and facilitating gout." (PMID 32630231, 2020). "Colchicine’s activity in gout may be partially rooted in this anti-inflammasome mechanism, as IL-1β is a key mediator of gouty arthritis." (PMID 33375692, 2020). "Importantly, we have demonstrated that wedelolactone indeed suppressed caspase 1 (p20) and IL‐1β expression in MSU‐induced gouty arthritis." (PMID 32656909, 2020). "NLRP3 inflammasome and IL-1β are important inflammatory triggers during gout flare." (PMID 33365024, 2020). "Therefore, hypermethylation of UBAP1 potentially reduces UBAP1 transcription and intensifies IL-1β production, exacerbating gout." (PMID 32630231, 2020). "In addition, β-carotene was shown to decrease IL-1β secretion by human synovial cells isolated from gout patients, demonstrating the potential inhibitory effect of β-carotene on human gout." (PMID 33603747, 2020). "IL-1β is a critical factor in that gout is primarily initiated by this cytokine." (PMID 32395118, 2020). "The results further demonstrated that gallic acid could alleviate MSU-induced gouty arthritis by inhibiting IL-1β expression." (PMID 33365024, 2020).
gout (continued). "Finally, mechanistic studies showed that MSU induces MDSCs to secrete IL-1β, which contributes to the gout inflammatory response." (PMID 33154749, 2020). "Likewise, it has also demonstrated that a high level of IL-1β can be detected in the sera of gout patients." (PMID 30863362, 2019). "Therefore, we further examined IL-1β release in gout via the NF-κB and the NLRP3 signaling pathways, respectively, to explore the mechanism of the antigout effect of chicory extract." (PMID 31590257, 2019). "The aims of this study are to investigate the role of oxidative stress on IL-1β production in primary human monocytes isolated from people with a history of gout by focusing on intracellular and extracellular antioxidant defenses rather than on the more commonly studied ROS." (PMID 30761138, 2019). "Among these pathways and genes, NOD-like receptor signaling pathway may play an important role in the curative effect of JSCBR on gouty arthritis by regulation of NRLP3/ASC/CASP1/IL1B." (PMID 32082152, 2019). "Additionally, interleukin-1 beta (IL-1β), a strong stimulator of bone resorption, can be produced in the inflammatory cascades during gout." (PMID 31455330, 2019). "The first step of nuclear factor kappa-B (NF-κB) activation is required to stimulate the expression of pro-IL-1β, and the maturation of IL-1β regulated by the NBD leucine-rich family (NLR) pyrin-containing 3 (NLRP3) inflammasome is the second key step in the initiation of gout flare." (PMID 31590257, 2019). "Thus, gout presents a unique opportunity to investigate the factors that contribute to IL-1β production, and in particular the role of oxidative stress on this process, as uric acid has both pro-and anti-oxidant effects depending on location and context." (PMID 30761138, 2019). "Gout is caused by precipitation of uric acid from the blood into insoluble crystals of monosodium urate (MSU) that can accumulate in joints and activate the NLRP3 inflammasome resulting in secretion of IL-1β." (PMID 30761138, 2019). "IL-1β is a key cytokine in gout inflammation considering the importance of NLRP3." (PMID 30914954, 2019). "Indeed, the oral administration of sulforaphane dose-dependently attenuated foot swelling and neutrophil recruitment while decreasing foot Il-1β levels and caspase-1 activity in animals with acute gout induced by MSU and air pouch." (PMID 31200447, 2019). "In addition, direct effects of pioglitazone in a rat model of gout have been reported and associated with reduced synovial cytokine (TNFα, IFN-γ and IL-1β) levels." (PMID 30202096, 2018). "It is likely that the increase in IL-6 in gout is a biomarker for active IL-1β." (PMID 30075804, 2018). "Recently, the result of the CANTOS clinical trial testing the use of Canakinumab monoclonal anti-IL1b antibody in gout patients has shown a reduction in cardiovascular events, therefore providing further support to the link between excessive inflammatory response and increased CVR36." (PMID 29651025, 2018). "The maturation of IL-1β is one of the main mechanisms of gout pathology." (PMID 30228306, 2018). "To find out whether miR-302b regulates proinflammatory cytokines in the pathogenesis of gout, in the present study with bioinformatics and genetic approaches we defined that miR-302b fine-tuned IL-1β production by targeting the NF-κB pathway." (PMID 29482609, 2018). "IL-1β plays a key role in initiation of the acute gout flare." (PMID 30201038, 2018). "In addition, NE cleaves pro-IL-1β into its bioactive IL-1β and IL-1β is a crucial cytokine of the inflammatory response in gout." (PMID 30034398, 2018). "This beneficial anti-gouty arthritis effect may be mediated, at least in part, by inhibiting the production of IL-1β and TNF-α." (PMID 28623927, 2017). "Active IL-1β is released into the extracellular joint fluid of patients with gout." (PMID 28915828, 2017).
gout (continued). "However, gout patients produced higher concentrations of IL-1β than the hyperuricemia patients following MSU + ATP stimulation [(131.08 ± 176.11) pg/ml vs. (50.84 ± 86.10) pg/ml, P = 0.012)]." (PMID 28797095, 2017). "The key role that IL-1β plays in gout and pseudo-gout was further confirmed by the effectiveness of blocking agents to IL-1 in that it reduced acute attacks, initially observed after the administration of IL-1Ra anakinra, and then to the anti-IL-1β monoclonal antibody canakinumab." (PMID 28588495, 2017). "While, at the early stage of gout flares, IL-1β drives inflammation, PMN recruitment and activation (proinflammatory segment), NETs become important later when sufficient levels accumulated capable of aggNET formation and cytokine degradation (anti-inflammatory phase)." (PMID 28373994, 2017). "In addition, monocytes from gout patients exhibited anti-inflammatory as well as pro-inflammatory activity, demonstrated by the production of IL-1β, IL-8, TNF-α, and IL-10." (PMID 29056937, 2017). "IL-1β is the major mediator that induces acute gouty arthritis." (PMID 28797095, 2017). "However, MSU + ATP stimulation produced higher IL-1β concentrations in gout patients than those in hyperuricemia patients." (PMID 28797095, 2017). "However, some hyperuricemia patients, even gouty patients with tophi in the joints, never experience gout attack, which indicates that pathogenic pathways other than MSU participate in the secretion of IL-1β in the pathogenesis of acute gouty arthritis." (PMID 28797095, 2017). "Here, we found that HG could significantly decrease the increased expression of TNF-α and IL-1β in rats with gouty arthritis." (PMID 26989428, 2016). "TNF-α and IL-1β are thought to be particularly important in the pathogenesis of gouty arthritis." (PMID 26989428, 2016). "A possible explanation for these observations is that patients with gout present with monosodium urate crystal-mediated inflammatory cytokines including tumor necrosis factor-α (TNF-α) and interleukin-1β (IL-1β), which have been implicated in the pathogenesis of myocardial dysfunction." (PMID 26568484, 2015). "Furthermore, a reduced pain was obtained following the treatment of patients with chronic active gouty arthritis with rilonacept, an inhibitor of IL-1β." (PMID 24438745, 2014). "By contrast, in gout, a 'hot' inflammation, thermal hyperalgesia may be more important, and in gout neutralization of IL-1β is analgesic." (PMID 25606597, 2014). "Targeting the inflammasome may therefore benefit joint pathologies allied with IL-1β production, such as OA, Muckle-Wells syndrome (an autoinflammatory disorder linked with mutations in NLRP3) and gout." (PMID 25175678, 2014). "In particular, the elevated levels of pro-inflammatory cytokines, such as IL-1β and TNF-α, in the synovial fluid of patients with gout, may be associated with miR-155-mediated regulation of monocyte/macrophage responses to MSU crystals." (PMID 24708712, 2014). "Recently, randomized controlled trials found that two anti-IL-1β biologic agents (rilonacept and canakinumab) prevented gouty arthritis during the initiation of urate-lowering therapy with allopurinol, but only canakinumab demonstrated efficacy for acute gouty arthritis." (PMID 24432362, 2013). "IL-1β has been identified as a pivotal cytokine in gout and MSU crystal-induced inflammation." (PMID 22608202, 2012). "In gout, for example, UA crystals have been shown to induce IL-1β production through the NALP3 inflammasome pathway; whether P. falciparum-derived UA precipitates activate immune cells via this mechanism has not yet been investigated." (PMID 23071567, 2012). "Moreover, colchicine, which is commonly used to treat gout and pseudogout, was found to dampen inflammasome-triggered IL-1β production." (PMID 23087690, 2012). "The most likely explanation is increased cleavage of pro-IL-1β to IL-1β in patients with gout." (PMID 22762240, 2012).
gout (continued). "In addition, the IL-1β response in the presence of C18:0 fatty acids together with MSU is augmented in the majority of the gout patients." (PMID 22762240, 2012). "Furthermore, we focused on the effect of Mangifera indica leaf on the induction of inflammatory cytokines TNF-α and IL-1β in gouty arthritis to investigate its anti-inflammatory mechanism." (PMID 23304232, 2012). "Inflammasome activation and IL-1β production are important inflammatory responses in a number of pathogens or conditions such as Muckle-Wells syndrome, Ebola virus, Marburg virus, gout, pseudogout, Crohn’s disease, asbestosis, silicosis, Systemic Inflammatory Response Syndrome (SIRS), etc.." (PMID 22792226, 2012). "There is evidence to suggest that IL-1β may also contribute to joint destruction in Gouty Arthritis." (PMID 21439048, 2011). "Our data provide novel insight in the role of IL-1β in the inflammatory milieu of gout." (PMID 22195044, 2011). "Gout is a prevalent inflammatory arthritis affecting 1–2% of adults characterized by activation of innate immune cells by monosodium urate (MSU) crystals resulting in the secretion of interleukin-1β (IL-1β)." (PMID 22195044, 2011). "MSU crystals induce secretion of interleukin-1β (IL-1β), a proinflammatory cytokine that mediates the inflammation that is characteristic of Gouty Arthritis flares and that may remain present between flares." (PMID 21439048, 2011). "Recent studies suggest that blockade of the NLRP3 (cryopyrin) inflammasome interleukin 1β (IL1β) pathway may offer a new treatment strategy for gout." (PMID 19635719, 2009). "Gouty arthritis is a metabolic disorder caused by purine metabolism dysregulation, characterized by monosodium urate crystal deposition in and around joints, triggering acute articular inflammation via NLRP3 inflammasome activation and IL-1β-mediated inflammatory cascades." (PMID 41583434, 2025). "Moreover, gout post‐OA synovial organoids showed higher IL‐1β levels." (PMID 39764563, 2025). "Additionally, these findings suggest that IL-1β could serve as a specific biomarker for acute gout inflammation." (PMID 40771212, 2025). "Two studies evaluated the effect of colchicine in GA, and the combination of colchicine treatment showed no significant improvement in uric acid, but could upregulate expression of miR-223-3p and miR-451a, downregulated COX-2 and IL-1β and treated with colchicine had fewer acute gout flares." (PMID 39775222, 2024). "Given that IL-1β is a major cytokine produced in response to MSU deposition and NLRP3 inflammasome activation is strongly linked to the development of gouty arthritis, targeting the NLRP3 inflammasome may be an effective therapeutic strategy for this condition." (PMID 39861092, 2024). "IL-1β further promotes the release of other cytokines, such as tumor necrosis factor-alpha (TNF-α) and interleukin-6 (IL-6), and the recruitment of neutrophils, perpetuating the inflammatory response and causing the severe pain and swelling characteristic of gout flares." (PMID 39409183, 2024). "Moreover, IL-1β blockers can significantly improve the symptoms of acute gouty arthritis." (PMID 39100670, 2024). "In addition, the secretion of the inflammatory cytokine IL-1β, an important inflammatory mediator in acute gouty arthritis, is one of the major clinical manifestations of the early onset of gout and is the initiating factor of inflammatory signaling activation." (PMID 38708084, 2024). "Some studies have suggested that MSU crystals can activate autophagy and reduce autophagy flux at the basal level, while the Inhibition of autophagy significantly increases the level of IL-1β, suggesting that autophagy may negatively regulate the inflammatory response of gout." (PMID 37069596, 2023).